YTHDC1 (YTH N6-methyladenosine RNA binding protein C1)
Diseases named in the same sentence as YTHDC1 in open-access papers (continued):
Sharing a sentence is not in itself a finding about the gene and the disease.
tumor (continued). "Importantly, YTHDC1-directed RBM4 splicing is governed by AURKA accumulated in the nucleus of cancer cells, therefore targeting AURKA with its nuclear translocation inhibitors effectively suppresses the oncogenic switch of RBM4 and tumor progression." (PMID 35361747, 2022). "Finally, 8 genes related to anti-tumor immunity were obtained, which were APOL3, CCL5, CD8A, CD8B, CXCL9, GZMA, GZMK and PRF1.We found that the m6A regulatory factors YTHDC1, YTHDC2, and WTAP were positively correlated with m6A, while IGF2BP3 was negatively correlated." (PMID 34737950, 2021). "Furthermore, the data indicated a negative correlation between XIAP and YTHDC1 in tumor samples." (PMID 40133252, 2025). "In the present study, our analysis suggests that expression levels of the ‘writers’ METTL3 and METTL14 and the ‘reader’ YTHDC1 are involved in HPV-dependent VSCC tumorigenesis, but not HPV-independent tumor development." (PMID 36050747, 2022). "We repeated this model using another TNBC cell line overexpressing YTHDC1, SUM159, and likewise found significantly higher levels of lung metastases without an increase in primary tumor size compared to control mice." (PMID 35966596, 2022). "However, we found YTHDC1, ZCCHC4, IGF2BP1 were not differently expressed between normal and tumor samples." (PMID 33748145, 2021).
cancer (80 papers, 2013 to 2025). A tumor composed of atypical neoplastic, often pleomorphic cells that invade other tissues. "Results indicated that lower levels of YTHDC1 are associated with increased cancer cell invasion and migration." (PMID 39741187, 2025). "Herein, the gain- and loss-of-function experiments showed that YTHDC1 inhibited mitochondrial respiration and malignant progression of OC cells, suggesting the anti-cancer role of YTHDC1 in OC." (PMID 39827178, 2025). "The artificial anchoring of YTHDC1 to m6A-deficient MALAT1 notably rescues the metastatic potential of cancer cells." (PMID 38255219, 2024). "YTHDC1 is a “reader” of m6A methyltransferases and is associated with functions including mRNA splicing, nuclear export, and stability, along with playing a role in anti-cancer." (PMID 39827178, 2025). "In current study, the SNV in the 5’-UTR region of the YTHDC1 gene, which is identified only in malignant tumors, may be associated with increased expression of the gene." (PMID 41168812, 2025). "Moreover, the dysregulated expression of YTHDC1 was associated with worse outcome, demonstrating that YTHDC1 may have the potential role as a biomarker and target for cancer treatment." (PMID 35501308, 2022). "We also aimed to explore the ability of YTHDC1 to modulate cancer invasiveness through m6A-dependent mechanisms." (PMID 39741187, 2025). "The study concludes that YTHDC1 is crucial in preventing cancer spread by regulating specific genes." (PMID 39741187, 2025). "The immunomodulatory role of the top-ranked gene, YTHDC1, has been extensively investigated in other cancer types." (PMID 40370450, 2025). "The MIDN level was correlated with several immune checkpoint genes, such as VEGFA, and RNA modification genes such as YTHDF1, YTHDF2, YTHDF3, and YTHDC1 in cancers." (PMID 40002690, 2025). "The expression levels of YTHDC1 and SRSF3 have been reported associated with the development of various cancers, including breast cancer, colorectal cancer, ovarian cancer, osteosarcoma, gliolastoma, and prostate cancer." (PMID 38365891, 2024). "Furthermore, while YTHDC1 has been associated with the initiation and progression of diverse cancer types, a direct mechanistic correlation between its gene regulatory activities and the consequential biological impact on crucial cancer pathways has yet to be firmly established." (PMID 38951610, 2024). "We discovered that FAM110B expression often showed a favorable correlation with pan-cancer gene expression associated with m1A, m5C, and m6A, particularly in YTHDF3, YTHDC1, NSUN3, TET2, and METTL14." (PMID 39170745, 2024). "Increasing evidence revealed the pioctal role of YTHDC1 in cancer through its involvement in alternative splicing of mRNA precursors." (PMID 38365891, 2024). "YTHDC1 is one of the m6A readers that play critical roles in different cancers, and a high concentration of YTHDC1 was reported in CRC cells and tissues." (PMID 39136000, 2024). "The Cancer Cell Line Encyclopedia (CCLE) database was used to obtain an expression matrix of YTHDC1 in various GBM cell lines." (PMID 39090090, 2024). "YTHDC1 has been identified as a critical regulator of tumorigenesis, drug sensitivity, and resistance in several cancers." (PMID 36609444, 2023). "In ESCC, LncMALAT1 acts as a molecular scaffold to bind to YTHDC1, which is crucial for the maintenance of NSs and the expression of related oncogenes, thereby promoting cancer cell metastasis." (PMID 36854773, 2023). "KEGG enrichment analysis of the RNA-seq data showed that YTHDC1 silencing upregulated many cancer-related pathways, including the Hippo, TNF, MAPK, VEGF, and PI3K-AKT-mTOR signaling pathways." (PMID 37258572, 2023). "LncMALAT1 binds to YTHDC1 as a molecular scaffold to maintain its nuclear localization and related oncogene expression, ultimately promoting metastasis of cancer cells." (PMID 36854773, 2023).
cancer (continued). "We found that high HOTAIR levels were only significantly associated with decreased survival in the context of high YTHDC1 mRNA, suggestive of a role for YTHDC1 in enhancing HOTAIR’s ability to mediate more aggressive cancer." (PMID 36441764, 2022). "YTHDC1 has recently been discovered to have an important function in stem cells and cancer progression." (PMID 36411870, 2022). "Emerging studies have shown that YTHDC1, an important m6A reader, plays a key role in many biological functions and disease progression, especially cancers." (PMID 35501308, 2022). "Meanwhile, emerging evidence also indicated that YTHDC1 is vital in several cellular functions, such as cancer cell proliferation, angiogenesis, chemoresistance and metastasis." (PMID 35501308, 2022). "We rechecked the RNA-seq data of YTHDC1 and found that Annexin-A1 (ANXA1) was upregulated after knockdown of YTHDC1 in cancer cells." (PMID 35974388, 2022). "In this review, our team outlined the biological functions of m6A reader YTHDC1 and more importantly, the potential role of YTHDC1 in cancers and other diseases." (PMID 35501308, 2022). "Of note, a Kyoto Encyclopedia of Genes and Genomes (KEGG) enrichment analysis indicated that YTHDC1 inhibition activated the EGFR tyrosine kinase inhibitor resistance pathway in cancer." (PMID 35974388, 2022). "Some studies have analyzed the relationship between YTHDC1, YTHDC2 gene variation, and cancer susceptibility." (PMID 36072379, 2022). "In CRC, m6A reader YTHDC1 expedited cytoplasmic export of circNSUN2 to promote cancer liver metastasis via stabilizing HMGA2, which acted as a driver of cancer metastasis via enhancing EMT process." (PMID 34745970, 2021). "In fact, experimental studies support the implications for YTHDC1 in cancer progression with regard to angiogenesis, growth factor signaling, immortalization, genetic instability, tissue invasion and apoptosis." (PMID 24401680, 2014). "Notably, YTHDC1 expression was higher in normal tissues and early-stage cancer, exhibiting a positive correlation with LncPTEN1 levels." (PMID 40521243, 2025). "Notably, SMAD6 mRNA colocalized less with YTHDC1 in tumoral tissues than in paratumoral tissues, indicating disrupted binding during cancer progression." (PMID 39741187, 2025). "This study investigates how YTHDC1 influences the invasiveness of cancer cells." (PMID 39741187, 2025). "Additionally, the nuclear m6A reader YTHDC1 has been shown to exert an important role in modulating many biological processes and contributing to disease, especially cancers." (PMID 40307231, 2025). "Importantly, our study demonstrates that YTHDC1-mediated mRNA regulation significantly impacts the genomic stability of cancer cells." (PMID 38951610, 2024). "Additionally, YTHDC1 is upregulated in several cancers, suggesting a cancer-promoting role of YTHDC1." (PMID 39090090, 2024). "However, the role of YTHDC1 in different cancer types remains a subject of debate among researchers studying m6A readers." (PMID 38565940, 2024). "YTHDC1 has alternative pre-mRNA splicing ability, and is closely related to cancer." (PMID 37856510, 2023). "YT521 (YTHDC1) is characterized by alternately spliced isoforms with regulatory impact on cancer." (PMID 36904058, 2023). "In addition, YTHDC1 was found to promote cancer progress in LIHC and PRAD, and play a protective role in COAD, BRCA, KIRP and KIRC." (PMID 37833468, 2023). "Notably, YTHDC1 plays critical roles in different cancers, and the elevation of YTHDC1 is observed in CRC cells and tissues." (PMID 36446779, 2022). "We first studied the clinical characteristics of YTHDC1 in malignant tumors." (PMID 35974388, 2022). "Several studies have reported the difference in YTHDC1 expression in a variety of cancers." (PMID 35563766, 2022).
cancer (continued). "Although the altered expression of YTHDC1 has been linked with m6A modification machinery and the effect on oncogenic factors, such as BRCA2 or PGR, it has yet to be addressed how YTHDC1 affects splicing or export in cancer cells." (PMID 35563766, 2022). "However, as an m6A reader, the specific function of YTHDC1 in various types of cancer is controversial." (PMID 35974388, 2022). "Studies have demonstrated that YTHDC1 may promote tumorigenesis, cell proliferation, and cancer cell migration." (PMID 36171892, 2022). "To further confirm the role of YTHDC1 in regulating cancer stem cells in HNSCC, we analyzed online HNSCC single-cell transcriptomic data to investigate YTHDC1 expression patterns at the single-cell level and the correlation of these levels with the expression of stem cell markers." (PMID 36411870, 2022). "We also explored the cancer-related role of YTHDC1 in ccRCC." (PMID 35974388, 2022). "Amongst splice factors, hypoxia also induces alternative splicing of the ubiquitous splicing factor YT521 (YTHDC1), switching expression to two non-coding YT521 variants 2 and 3 mRNAs, functionally coupled to nonsense mediated decay, that impact the splicing of cancer-associated BRCA2 and PGR." (PMID 32536347, 2020). "In AML cells, YTHDC1 requires m6A for liquid–liquid phase separation to form nuclear YTHDC1–m6A condensates, protecting m6A–mRNAs from degradation via the PAXT complex and exosome‐associated pathways, thereby maintaining mRNA stability and regulating cancer cell survival and differentiation." (PMID 40761481, 2025). "However, the role of YTHDC1 in malignant tumors is controversial." (PMID 37258572, 2023). "Thus, YTHDC1 can affect not only mRNA but also other RNA, including circRNA, in cancer." (PMID 35563766, 2022). "Together, our results support a mechanism where YTHDC1 interaction specifically at m6A783 leads to repression of HOTAIR genomic targets, and that this direct action causes further gene expression changes, cumulatively promoting HOTAIR- and m6A-dependent cancer cell phenotypes." (PMID 36441764, 2022). "Therefore, it is possible that part of the proteomic diversity in cancer cells may be regulated by unknown mechanisms that derive from m6A- deposited RNA splicing or export with YTHDC1 or SR proteins, including their various phosphorylation statuses." (PMID 35563766, 2022). "Positive correlations between the expression of YTHDF3, YTHDF2, YTHDF1, and YTHDC1 and MIDN levels were detected in nearly all cancers." (PMID 40002690, 2025). "In AML, the nuclear m6A reader YTHDC1 promotes the formation of m6A-containing mRNA condensates, stabilizing oncogenic transcripts like MYC mRNA and promoting cancer cell survival." (PMID 39085650, 2024). "This study is aimed at investigating the role of YTHDC1 in HNSCC and exploring its role in regulating cancer stem cells." (PMID 36411870, 2022). "This specific site, bound by YTHDC1, is critical for promoting HOTAIR-dependent cancer phenotypes and gene expression in TNBC cells." (PMID 36441764, 2022). "An increasing number of studies have confirmed that m6A writers (METTL3, METTL14, KIAA1429, WTAP), erasers (FTO and ALKBH5) and readers (YTHDC1, YTHDC2, YTHDF1, YTHDF2 and HNRNPC) have distinct functions within different types of cancer cells." (PMID 35042525, 2022). "Altogether, this study reveals an undetermined role for YTHDC1 in HNSCC, suggesting its potential use as a prognostic marker and therapeutic target for this cancer." (PMID 36411870, 2022). "The other three YTH family proteins, YTHDF3, YTHDC1, and YTHDC2, were found to be less correlated with human cancer than YTHDF1 and YTHDF2." (PMID 33795663, 2021). "Furthermore, the decreased expression of YTHDC1 is correlated with the expression of markers of EMT, a critical process that promotes cancer invasion and metastasis." (PMID 39741187, 2025).
cancer (continued). "However, the expression of WTAP, YTHDC1 and FASN was increased in NAFLD/NASH/HCC samples, indicating m6A-dependent downregulation of AP-2α during the inflammation-cancer progression." (PMID 40180937, 2025). "In addition, m6A‐recruited the binding proteins, YTHDC1, YTHDC2, YTHDF3, and FMR1 were inversely correlated, while HNRNPC, HNRNPA2B1, YTHDF1, and RBMX positively correlated TSs in most cancer types." (PMID 36239411, 2023). "We first found that YTHDC1 mRNA expression was downregulated in cancer tissues compared with nontumor tissues, and there was a positive association between YTHDC1 and miR-30d and a negative association between YTHDC1 and RUNX1, SLC2A1, HK1." (PMID 34021267, 2021). "Besides that, HNRNPA2B1, YTHDC1, METTL14, WTAP, and ZC3H13 were downregulated in cancer tissues, whereas VIRMA had opposite alterations between these two databases." (PMID 33225598, 2021). "Compared with the control group, expression levels of HNRNPC, YTHDF1, KIAA1429, RBM15, YTHDF2, and METTL3 in cancer group were significantly up-regulated (P < 0.05), while expression levels of FTO, ZC3H13, METTL14, YTHDC1, and WTAP in cancer group were significantly down-regulated (P < 0.05)." (PMID 33193582, 2020). "Although YTHDF2, YTHDF3, and YTHDC1 showed essential roles in multiple cancer types, to date, no research on these regulators in COAD has been conducted." (PMID 32596399, 2020). "In conclusion, akin to METTL3, METTL4, METTL16, WTAP, RBM15/15B, VIRMA, and ZC3H13, the potential influence of YTHDC1, YTHDC2, YTHDF, IGF2BPs, the HNRNP family, eIF3, FTO, and ALKBH3/5 on autophagy is intertwined with their roles in RNA metabolism, collectively regulating autophagy in cancer." (PMID 38148841, 2023). "Notably, the coupled increase of YTHDC1 and DDX5 expression in a larger set of human cancers suggests that both factors might be relevant for the biogenesis of specific subsets of circRNAs in tumors other than RMS." (PMID 37019933, 2023). "The expression of YTHDF2 in cancer tissues was also up-regulated (p < 0.05), while those of RRP8, YTHDC1, and YTHDF3 were not significantly different." (PMID 34195072, 2021).
infection (6 papers, 2017 to 2025). The state of being infected such as from the introduction of a foreign agent such as serum, vaccine, antigenic substance or organism. "More specifically, we show that YTHDC1 suppresses the early infection of RSV via downregulation of CX3CR1 on the host cell." (PMID 38793659, 2024). "Because the amount of genomic RNA transcripts is affected early in infection, these results indicate a role for YTHDC1 in the regulation of viral entry." (PMID 38793659, 2024). "As we observed that YTHDC1 reduced RSV viral load early after infection, we next investigated the mechanism behind this observation." (PMID 38793659, 2024). "Overexpression of YTHDC1 resulted in a reduced number of cells infected with RSV-GFP as determined by flow cytometry 72 h post-infection." (PMID 38793659, 2024). "Co-transfection and co-infection experiments showed that both YTHDC1 and its W378A mutant, but not the YTHDC1 ∆IDR variant, were able to prevent ARIH2-induced degradation of PPARγ in HEK293T cells, primary brown adipocytes, and primary white adipocytes." (PMID 40355558, 2025). "Over the course of infection, levels of the assayed writers (METTL3, METTL14, and WTAP) and readers (YTHDC1, YTHDF1, and YTHDF2) remain unchanged." (PMID 33243990, 2020). "To determine whether YTHDC1-mediated differences in viral load are the result of decreased RSV infection of host cells, we performed single-molecule RNA fluorescence in situ hybridization (smFISH) with probes against genomic RSV RNA 2 h post-infection." (PMID 38793659, 2024). "YTHDC1 mRNA and protein expression were not impacted by RSV-GFP infection." (PMID 38793659, 2024).
neurodegenerative disease (2 papers, 2025). A disorder of the central nervous system characterized by gradual and progressive loss of neural tissue and neurologic function. "In our present study, four m6A feature regulators (YTHDC1, IGFBP1, IGF2BP1, and ALKBH5), critically implicated in psychiatric disorders and neurodegenerative diseases, were identified to be associated with PTSD." (PMID 41149057, 2025).
heart diseases (1 paper, 2021). "To understand the functional involvement of Ythdc1 in postnatal heart and potential contribution to heart diseases, we generated a conditional deletion allele of the mouse Ythdc1 gene." (PMID 34716659, 2021). "Our studies reported YTHDC1 participates in the onset and progression of DCM, providing new evidence that RNA modification involves in the processing of heart disease." (PMID 34716659, 2021).
immune diseases (1 paper, 2021). "Collectively, our data show that YTHDC1 is critical for microglial inflammatory response regulation and can serve as a target for the development of therapeutics for autogenic immune diseases." (PMID 34975410, 2021).
retinopathy (1 paper, 2024). "We will further explore the binding site of YTHDC1 methylation modification, explore other possible regulatory factors, and further understand the role of YTHDC1 in m6A methylation in retinopathy induced by HG." (PMID 38978074, 2024).
YTHDC1 also shares sentences with these, for which no sentence is quoted: lung squamous cell carcinoma (3 papers); colon cancer (2); esophageal cancer (2); gastric cancer (2); idiopathic pulmonary fibrosis (2); infertile (2); steatosis (2); acute respiratory distress syndrome (1); ankylosing spondylitis (1); Cerebral ischemia (1); cervical squamous cell carcinoma (1); colon adenocarcinoma (1); colorectal adenocarcinoma (1); COVID-19 (1); Crohn disease (1); depression (1); digestive system neoplasm (1); embryonal carcinoma (1); endometriosis (1); female sterility (1); Insulin resistance (1); Intellectual disability (1); Kaposi's sarcoma (1); leukopenia (1); Lung Injury (1); mastitis (1); metastatic melanoma (1); nonalcoholic steatohepatitis (1); osteoarthritis (1); psychiatric disorder (1).
A further 5 diseases each share a sentence with YTHDC1 in 1 paper.